NUP62 (nucleoporin 62)
Diseases named in the same sentence as NUP62 in open-access papers (continued):
Sharing a sentence is not in itself a finding about the gene and the disease.
colorectal cancer (1 paper, 2006). A primary or metastatic malignant neoplasm that affects the colon or rectum. "Among the up-regulated genes in colorectal cancer, we found 14 genes involved in signal transduction (TDGF1 and ENC1), transcription (SOX9, MYC, and HGFR/MET), nuclear transport (NUP62, NUPL1, NUP155, KPNA2, RANBP5, CSE1L/CAS, NTF2, and RANBP1) and cellular transport (SLCO4A1)." (PMID 16919171, 2006).
cyst (1 paper, 2019). A sac-like closed membranous structure that may be empty or contain fluid or amorphous material. "Depletion of Nup62, Nup214 or Nup88 in cyst cells led to cell-autonomous defects in mRNA export in Drosophila." (PMID 31492028, 2019).
dilated cardiomyopathy (1 paper, 2012). Cardiomyopathy which is characterized by dilation and contractile dysfunction of the left and right ventricles. "Specifically, it has been observed that the nucleoporin Nup62 is increased in patients with ischaemic and dilated cardiomyopathy." (PMID 23152829, 2012).
hepatoma (1 paper, 2012). "Moreover, ORP8 was found to physically interact with the nuclear pore complex component NUP62, and a normal level of NUP62 in HuH7 hepatoma cells was found to be necessary for the ORP8-mediated reduction of nuclear SREBPs." (PMID 24970128, 2012).
Hutchinson-Gilford progeria syndrome (1 paper, 2021). "Additionally, HeLa cells contained Hutchinson Gilford progeria syndrome (HGPS) mutation showed mislocalization of Nup62 and Nup153, decreased the lamina dynamics, and the impaired nuclear import." (PMID 33920577, 2021).
mesothelioma (1 paper, 2025). A usually malignant and aggressive neoplasm of the mesothelium which is often associated with exposure to asbestos. "The results indicate that high expression of NUP62 is significantly associated with shorter OS in KIRP, KIRC, ACC, LGG, LIHC, mesothelioma (MESO), skin cutaneous melanoma (SKCM), and SARC (p < 0.05)." (PMID 40098960, 2025).
metastatic prostate carcinoma (1 paper, 2025). A carcinoma that arises from the prostate gland and has spread to other anatomic sites. "In addition, elevated levels of other NUPs downregulated by bromoxib in TPP (i.e., NUP188, NUP210, NUP85, NUP62, and NUP214) were identified in metastatic prostate cancer, suggesting that NPC dysregulation may drive aggressive cancer phenotypes." (PMID 40137294, 2025).
Obesity (1 paper, 2025). Accumulation of substantial excess body fat. "We found that MORC3, NUP62, CGAS, ABI3, and RPA2 were highly expressed in lean individuals, where as LMNA, ID2, CDKN1A, TENT4B, MME, and MYC were upregulated in the PBMCs of individuals with obesity." (PMID 40847086, 2025).
oral cancers (1 paper, 2023). "We strengthened the observation made in cell line overexpression studies by analyzing p65 target genes in GEO & Oncomine oral cancer datasets already reported for Nup88 and Nup62 upregulation." (PMID 36845732, 2023). "Cancer RNA-Seq Nexus (CRN) analysis showed that Nup62 transcript levels are higher in progressive stages of oral cancer." (PMID 36845732, 2023). "Control gene (GAPDH) levels varied among patient samples, but the ratiometric analysis of Nup62 or Nup88 with GAPDH indicates that both Nups are significantly overexpressed in oral cancer tissues (n=4)." (PMID 36845732, 2023). "We find elevated Nup88 and Nup62 mRNA and protein levels in oral cancer tissues and a positive correlation between elevated Nup88 levels vis-a-vis poor survival rates." (PMID 36845732, 2023). "We also analyzed the co-expression of Nup62 and Nup88 in oral cancers in a collection of available datasets at MiPanda, and found that Nup62 and Nup88 transcript levels were significantly higher in primary tumors when compared to normal samples." (PMID 36845732, 2023). "Accordingly, invariably higher Nup62 protein levels were detected (~2 folds) upon analysis of additional oral cancer tissues (and S1c n=10)." (PMID 36845732, 2023). "We report significantly enhanced levels of Nup88 and Nup62 protein in oral cancers." (PMID 36845732, 2023).
poliovirus infection (1 paper, 2021). An disease or disorder caused by infection with Enterovirus C. "Later, it was shown that another FG-nucleoporin, NUP98, was also degraded during poliovirus infection, but at an earlier time of infection (around 2 h.p.i compared to 4 h.p.i for NUP153 and NUP62)." (PMID 34201715, 2021).
retinal degeneration (1 paper, 2022). Degeneration of the retina. "Therefore, to validate our initial screen and determine whether higher DPR levels enhance toxicity association with Nup62 downregulation, we also tested the impact of Nup62 knockdown on (G4C2)36Drosophila retinal degeneration." (PMID 35697676, 2022).
sarcoma (1 paper, 2025). A usually aggressive malignant neoplasm of the soft tissue or bone. "Gender differences in NUP62 expression levels are observed in sarcoma (SARC), KIRP, and the Pan-kidney cohort (KIPAN), with significantly higher expression in female patients compared to male patients." (PMID 40098960, 2025).
stomach cancer (1 paper, 2025). "Immunohistochemistry and RT-PCR were used to validate the expression of NUP62 in gastric cancer tissues." (PMID 40098960, 2025). "This study used multi-omics analyses combined with experimental validation in gastric cancer to investigate the expression, functional characteristics, and clinical relevance of NUP62 in cancer." (PMID 40098960, 2025). "Validation experiments demonstrated that NUP62 mRNA and protein levels were significantly higher in gastric cancer tissues than in adjacent normal tissues." (PMID 40098960, 2025). "Furthermore, through quantitative PCR analysis, we found that the mRNA expression level of NUP62 in gastric cancer tissues is also significantly elevated compared to their adjacent non-cancerous tissues." (PMID 40098960, 2025). "Additionally, we validated the differential expression of NUP62 between gastric cancer tissues and their adjacent non-cancerous tissues." (PMID 40098960, 2025). "To validate our initial hypothesis, we employed immunohistochemical techniques to conduct an in-depth analysis of NUP62 protein expression levels in gastric cancer tissues and their adjacent non-cancerous tissues." (PMID 40098960, 2025).
testicular cancer (1 paper, 2025). A primary or metastatic malignant neoplasm that affects the testis. "We noted a decreasing trend in the expression level of NUP62 in testicular cancer tissues, which contrasts with the upregulation of NUP62 expression in most cancers." (PMID 40098960, 2025). "By deeply exploring the expression regulation mechanism of NUP62 in testicular cancer, it is expected to provide new ideas and methods for the diagnosis and treatment of testicular cancer." (PMID 40098960, 2025).
uveal melanoma (1 paper, 2025). A melanoma derived from melanocytes of the uveal tract. "However, in uveal melanoma (UVM), BLCA, STAD, and CESC, high expression of NUP62 is associated with longer survival, potentially playing a protective role." (PMID 40098960, 2025).
ZIKV infection (1 paper, 2020). "Our results indicate that during DENV infection, the integrity and distribution of at least Nup153, Nup98, and Nup62 were disrupted, while during ZIKV infection, the integrity of TPR, Nup153, and Nup98 were altered." (PMID 32466480, 2020). "We found that while during DENV infection the integrity and distribution of at least three nucleoporins (Nup), Nup153, Nup98, and Nup62 were altered, during ZIKV infection, the integrity of TPR, Nup153, and Nup98 were modified." (PMID 32466480, 2020).
infection (17 papers, 2010 to 2025). The state of being infected such as from the introduction of a foreign agent such as serum, vaccine, antigenic substance or organism. "Additionally, MLV capsid associated with the nuclear pore proteins NUP358 and NUP62 during infection." (PMID 38215165, 2024). "In a few instances, (e.g. HIV-1WT infection of HT1080 cells and FIV infection of HeLa cells) depletion of Nup62 complex components modestly increased infection." (PMID 30084827, 2018). "Cleavage of Nup62 was also observable after infections with either L. mexicana or L. major using only low doses of infection." (PMID 25826301, 2015). "Proteolysis of these three FG-Nups have different kinetics with cleavage of Nup98 early, followed by Nup62 and Nup153 at later times post-infection, the latter coinciding with a block in import of multiple nuclear proteins." (PMID 23959328, 2013). "Indirect immunofluorescence at 3 hours post-infection demonstrates that Nup358, Nup214 and Nup62 are displaced into the cytoplasm and colocalize with disassembled virus particles at the cell periphery." (PMID 23959328, 2013). "Cells with efficient reduction of BIRC5 and NUP62 expression were strongly impaired in their viability when assayed eight days post-infection (BIRC5-A-C/NUP62-A-B)." (PMID 20051122, 2010). "Additionally, while Nup62 subcomplex depletion modestly enhanced HIV-1WT infection in control cells, depletion of members of this subcomplex slightly reduced infectivity in RANBP2∆Cyp cells." (PMID 39853118, 2025). "MX2 also modestly enhanced HIV-1WT infection upon NUP62, RAE1, and TNPO1 knockdown." (PMID 39853118, 2025). "Later during infection, other Nups have been reported to be targeted as well by both 2Apro (Nup62, Nup153, and Nup358), and by 3Cpro (Nup153, Nup214, and Nup358), but the extent to which these contribute to the NCTD is unknown." (PMID 40875754, 2025). "We observed that NUP98 protein levels were decreased both in SupT1 and HEK293T cell types upon HIV-1 NL4.3 infection by 4.7- and 1.5-fold, respectively (respectively), whereas the protein levels of other NUPs such as NUP62, NUP155, NUP133, NUP107, and NUP85 remained unaffected." (PMID 38449868, 2024). "NUP62 depletion did not significantly inhibit HIV-1WT infection of HeLa or HT1080 cells but caused a four-fold decrease of infection of non-dividing HOS cells." (PMID 30084827, 2018). "Additionally, a recent microarray study of mock and HIV-1-infected human primary CD4+ T lymphocytes indicates that Nup50 is downregulated and Nup62 is upregulated at 24 hours post-infection." (PMID 23959328, 2013). "In line with our observations, a recent report confirmed that FAM111A cleaves NUP62 and disrupts nuclear barrier during MVA infection, in addition to inducing the degradation of the viral single-stranded DNA-binding (SSB) protein I327." (PMID 38065956, 2023). "Infection by HIV-1N57S was strongly inhibited by CsA in HT1080 cells and Nup depletions partly (e.g. NUP62, NUP54, NUPL1) or nearly completely (e.g. NUP155, NUP205) abolished this CsA sensitivity." (PMID 30084827, 2018). "This emphasizes the likelihood of a Nup62 cleavage and consequently a NPC-degradation during in vivo parasite infections." (PMID 25826301, 2015). "Notably, 9 nucleoporins (NUP58, NUP214, NUP98, NUP54, NUP62, NUP88, NUP153, POM121/NUP121 and RANBP2/NUP358) and the mRNA export factor Rae1 were present in both the CebN infection and transfection interactomes." (PMID 38712050, 2024). "They noticed that two FG-nucleoporins, NUP153 and NUP62, were no longer detectable by western blot after 4.5 h of infection, a timing that correlated with nucleocytoplasmic trafficking perturbation." (PMID 34201715, 2021). "Furthermore, unlike during infection, we observed downregulation of the protein levels of NUP62 and NUP85 by 1.2- and 2.1-fold, respectively, whereas NUP133 was upregulated by 1.5-fold." (PMID 38449868, 2024).
infection (continued). "Unlike HIV-1WT, HIV-1G89V infection was modestly reduced (four-fold) upon NUP62 knockdown in HeLa cells, but HIV-1G89V infection was restored by MX2 expression in NUP62 depleted HeLa cells." (PMID 30084827, 2018). "The usage of a large array of virulent Leishmania species and the non-virulent L. tarentolae strain in infection experiments also indicated that the GP63-dependent alteration of the NPC, as shown by Nup62 cleavage, is a conserved phenomenon in virulent Leishmania species." (PMID 25826301, 2015).
cancer (13 papers, 2012 to 2025). A tumor composed of atypical neoplastic, often pleomorphic cells that invade other tissues. "Next, our research found that NUP62 expression is associated with the prognosis of cancer patients, with differential expression observed in different types of cancer patients, as confirmed by KM curves." (PMID 40098960, 2025). "Immunotherapy has emerged as a primary modality in cancer treatment, prompting our investigation into the potential association between NUP62 and cancer immunity." (PMID 40098960, 2025). "We evaluated the diagnostic capacity of NUP62 for various cancers in both the TCGA dataset and the combined TCGA-GTEx dataset." (PMID 40098960, 2025). "NUP62, a key component of the nuclear pore complex, is closely associated with cellular functions and cancer progression." (PMID 40098960, 2025). "The significant negative correlation of NUP62 with CTLA-4 may imply that the low expression of NUP62 in these two cancers is associated with an attenuated immunosuppressive state." (PMID 40098960, 2025). "Furthermore, numerous studies have demonstrated that NUP62 mediates selective nucleocytoplasmic transport and is associated with various cancers through chromosomal translocations that generate fusion proteins, alterations in protein expression levels, and single-point mutations." (PMID 40098960, 2025). "The expression of NUP62 is also closely related to gender and age, which may be associated with hormones, cellular aging, decreased DNA damage repair capacity, and increased cancer risk." (PMID 40098960, 2025). "Therefore, NUP62 is an effective diagnostic biomarker across various cancer types." (PMID 40098960, 2025). "Furthermore, the expression of NUP62 is associated with various cancer stages." (PMID 40098960, 2025). "This further supports the idea that NUP62 serves as an important node in the cancer immunoregulatory network." (PMID 40098960, 2025). "To delve deeper into the potential roles and specific functions of NUP62 in cancer, we employed an integrated analysis of signature gene expression to assess the activity status of NUP62 pathways." (PMID 40098960, 2025). "NUP62 plays a critical role in multiple cancers and shows potential as a biomarker for cancer diagnosis, prognosis, and therapeutic response prediction." (PMID 40098960, 2025). "The results indicated that NUP62 expression is generally higher in cancer cells compared to normal cells." (PMID 40098960, 2025). "This suggests that NUP62 can serve as a prognostic marker for some cancers to guide the selection of treatment regimens for cancer patients, taking into account individual differences and formulating personalized treatment plans." (PMID 40098960, 2025). "These pathways and processes play crucial roles in cancer cell proliferation, invasion, metastasis, and drug resistance, emphasizing the complexity and diversity of NUP62 in tumors." (PMID 40098960, 2025). "In the TCGA dataset and the combined TCGA-GTEx dataset, NUP62 exhibited high AUC values across various cancers." (PMID 40098960, 2025). "To gain deeper insights into the clinical significance of NUP62 in the field of cancer, we analyzed its prognostic value in multiple malignant tumors." (PMID 40098960, 2025). "Subsequently, we investigated the relationship between NUP62 and TCPA functional proteins, further demonstrating the important role of NUP62 in regulating the cell cycle of cancer patients." (PMID 40098960, 2025). "Our results indicate that across various cancer types, the expression level of NUP62 significantly correlates with the expression of immune-related genes, such as those in THCA, KIRC, KIRP, and PCPG." (PMID 40098960, 2025). "The analysis revealed that Nup62 as well as Nup88 levels are upregulated in all different types of cancers analyzed, like the cancers of head and neck, breast, and stomach." (PMID 36845732, 2023).
cancer (continued). "We asked if Nup88 and Nup62 can interact as reported in yeast to mediate the Nup88 overexpression dependent cancer phenotypes." (PMID 36845732, 2023). "Overexpression of Nup62 promotes colony formation and cell migration in cancer gastric." (PMID 40006055, 2025). "In the subsequent analysis, we comprehensively analyzed the metabolic pathways in which NUP62 might be involved in pan-cancer by performing GSEA analysis on the KEGG metabolic gene set." (PMID 40098960, 2025). "Utilizing the TCGA database, we conducted an in-depth exploration of the interaction between NUP62 and functional proteins within the TCGA database, and found that NUP62 exhibits significant correlations with multiple key functional proteins across various cancer types." (PMID 40098960, 2025). "Together, our data indicate that when cancers overexpress Nup88, often Nup62 is co-expressed." (PMID 36845732, 2023). "Thus co-overexpression of Nup62 in cancers may probably work through the stabilization of Nup88, and stable Nup88 can engage in proliferative activities inducing tumorigenic transformation." (PMID 36845732, 2023). "Furthermore, another recent study identified the Nup62 as a novel regulator of nuclear import of p63 that is an essential transcription factor for proliferation and maintenance of the undifferentiated status of human carcinoma cells." (PMID 31979075, 2020). "Moreover, previous studies have demonstrated that NUP62 can maintain the spindle assembly checkpoint downstream of kinetochores, thereby ensuring maintenance of chromosomal stability, indicating that NUP62 may participate in another potential mechanism of human cancer development." (PMID 39080077, 2024). "Alternatively, the MUC1-C oncoprotein directly binds the central domain of NUP62, and this interaction is required both for nuclear import and for the oncogenic manifestations of MUC1-C over-expression in carcinoma cells." (PMID 22558357, 2012). "The significant correlation of NUP62 with the expression of immune-related genes (e.g., THCA, KIRC, KIRP, and PCPG) in multiple cancer types suggests that it may play a role in a wide range of immune regulatory processes." (PMID 40098960, 2025). "This suggests that NUP62 expression in these cancers may not be the primary factor promoting immune evasion or that it interacts in a complex manner with other immune regulatory mechanisms." (PMID 40098960, 2025).